AXIN1 (axin 1)
Diseases named in the same sentence as AXIN1 in open-access papers (continued):
Sharing a sentence is not in itself a finding about the gene and the disease.
colorectal cancer (continued). "Lastly, in the colorectal cancer cell line SW480 that also possesses a truncating APC mutation, tankyrase RNAi stabilizes AXIN1, AXIN2, and RNF146 proteins." (PMID 21799911, 2011). "Taken together, our data suggest that AXIN2 promotes degradation of AXIN1 through TNKS in colorectal cancer cells by directly linking the two proteins, and these findings may be relevant for TNKS inhibition‐based colorectal cancer therapies." (PMID 39022865, 2025). "USP44, for instance, reduces AXIN1 ubiquitination to inhibit colorectal cancer cell proliferation." (PMID 38291457, 2024). "Moreover, we demonstrated that it is sufficient to enhance the activity of AXIN2 to inhibit Wnt signaling in colorectal cancer in spite of the rather small amount of AXIN2 compared to AXIN1, which is consistent with a high importance of AXIN2 for regulating Wnt signaling in cancer cells." (PMID 39022865, 2025). "AXIN1 and AXIN2 are homologous proteins that inhibit the Wnt/β‐catenin signaling pathway, which is frequently hyperactive in colorectal cancer." (PMID 39022865, 2025). "Our proposed mechanism of AXIN2‐induced degradation of AXIN1 will correlate with the expression levels of AXIN2 and therefore will be most active in colorectal cancer cells expressing high AXIN2 levels." (PMID 39022865, 2025). "TNKS small‐molecule inhibitors block Wnt/β‐catenin signaling by stabilizing AXIN1 and AXIN2, and have therefore been investigated for targeted treatment of colorectal cancer." (PMID 39022865, 2025). "Together, our study uncovers an important regulatory mechanism of Axin1 polymerization and implies that targeting TRIM15 provides a therapeutic strategy for colorectal cancer based on inhibiting Wnt signaling." (PMID 41461634, 2025). "Prossomariti and colleagues revealed that miR-155-5p interacts with the 3'UTR of AXIN1, leading to sustained WNT/β-catenin activation in colorectal cancer cells." (PMID 38291457, 2024). "In an orthotopic colorectal cancer mouse model, we demonstrated that a 5-HT1DR antagonist (GR127935) effectively inhibited tumor metastasis through targeting Axin1." (PMID 26214021, 2015). "The findings from this study revealed an inherent role of 5-HT1DR which binds Axin1 and dissociates β-catenin from the complex, moving β-catenin into the nucleus to activate the β-catenin/LEF1/TCF4/MMP-7 pathway in colorectal cancer metastasis." (PMID 26214021, 2015). "Because increased motility and invasion are among the principal effects of upregulated Axin1/β-catenin signaling, those features were tested in 5-HT1DR overexpressing colorectal cancer cells." (PMID 26214021, 2015). "Because pathway activation by Wnt ligands plays a role in colorectal cancer, the reduced inhibitability of AXIN2 compared to AXIN1 could potentially explain its special importance." (PMID 39022865, 2025). "In colorectal cancer (CRC) cells, the β-catenin destruction complex component AXIN1 is ubiquitinated and degraded as a result of the interaction between the E3 ubiquitin ligase SIAH1 and AXIN1, which is facilitated by CK1ε." (PMID 39223632, 2024). "Additionally, the POP112 line did not harbour mutations or deep amplifications or deletions in the WNT pathway members defined as colorectal cancer drivers APC, AXIN1, AXIN2, CTNNB1, GSK3B or RNF43, and only a shallow deletion in ZNRF3." (PMID 38324534, 2024). "Alternatively, treatment of BRAF mutant colorectal cancer models with MAPK inhibitors stimulated WNT pathway through the activation of cytoplasmic focal adhesion kinase (FAK) or depletion of AXIN1 protein, resulting in the stabilization of β-catenin." (PMID 33821796, 2021). "In SW480 colorectal cancer cells treated with the tankyrase inhibitor (TNKSi) G007-LK we found that AXIN1 was not required for degradasome formation." (PMID 28107521, 2017).
colorectal cancer (continued). "The immunoreactivity of GSK3β, axin 1 and ubiquitin proteins was significantly higher (p=0.03, p=0.039 and p=0.03, respectively) in colorectal carcinoma than in the colonic adenoma and adjacent non-neoplastic mucosa." (PMID 27462886, 2016). "Therefore, tumors displaying β-catenin, APC or AXIN1 mutation are considered to display active or constitutive canonical Wnt signaling Activation of canonical Wnt signaling appears to be a common event for colorectal cancer, as opposed to HCC with mutations limited to a subset of these cancers." (PMID 19849855, 2009). "Thus, the overcompensating increase in AXIN1 protein did not functionally compensate for β‐catenin degradation by AXIN2, pointing to a special importance of AXIN2 for Wnt pathway regulation in colorectal cancer cells." (PMID 39022865, 2025). "However, the expression level overcompensating increase of AXIN1 failed to rescue the decrease of AXIN2 functionally because knockout or knockdown of AXIN2 activated Wnt signaling, suggesting that AXIN2 is crucial for Wnt pathway regulation in colorectal cancer cells." (PMID 39022865, 2025).
breast carcinoma (23 papers, 2008 to 2025). "Axin1 was among the top 93 driver genes mutated in breast cancer, ranging between 3 and 5% across the different subtypes." (PMID 35000262, 2022). "It suggests that loss of RUNX1 in breast cancer facilitates ERα-mediated suppression of AXIN1, resulting in aberrant β-catenin signalling." (PMID 26916619, 2016). "It was recently determined that loss of Axin1 expression is a key event in breast cancer progression." (PMID 26908451, 2016). "Interestingly, IVM also decreased the expression of LRP6 and Axin1, proteins associated with activation at the Wnt receptor, in both endocrine-resistant breast cancer cell lines." (PMID 40569965, 2025). "Previous studies have implicated abnormalities in Axin1 and Prkar1a expression in breast cancer although their roles in normal development and oncogenesis remain unclear." (PMID 35000262, 2022). "Instead, E2-mediated AXIN1 suppression upon RUNX1 loss may contribute to ER+ breast cancer progression through mitotic aberrations that promote expansion of a stem cell-like population." (PMID 26916619, 2016). "In cancer, miR-124-3p promotes breast cancer progression by targeting the Axin1 protein, facilitating cancer cell proliferation." (PMID 40625748, 2025). "Further studies will be required to define the precise roles of Axin1 and Prkar1a in breast epithelial cells and the mechanisms by which defects in these genes contribute to breast cancer progression." (PMID 35000262, 2022). "Tumor suppressor protein AXIN1 deregulates β-catenin and mitosis to weaken the ER+ and ER− breast cancer." (PMID 31143301, 2019). "It further suggests that RUNX1 suppresses ER+ breast cancer progression by denying oestrogens their negative regulation of AXIN1." (PMID 26916619, 2016). "Taken together, our results assign a role for RUNX1 in antagonizing oestrogen-mediated AXIN1 suppression and highlight AXIN1 as a potential target for the treatment of RUNX1-deficient ER+ breast cancer." (PMID 26916619, 2016). "Our data therefore demonstrates crosstalk between oestrogen and β-catenin signalling in ER+ breast cancer through AXIN1." (PMID 26916619, 2016). "Here, we demonstrate that RUNX1 antagonizes oestrogen-mediated inhibition of AXIN1 expression, shedding light on its breast cancer suppression role." (PMID 26916619, 2016). "Our work marks AXIN1 as a potential therapeutic target to remedy deregulation of β-catenin in ER+ breast cancer tumours that have lost RUNX1 function through somatic mutations or other mechanisms." (PMID 26916619, 2016). "Axin1, recently determined to be a critical protein that is downregulated in breast cancer, targets β-catenin for degradation when complexed with APC, GSK-3β, and CKII." (PMID 26908451, 2016). "We show that application of the small molecule tankyrase inhibitor, XAV939 or siRNA-mediated abrogation of tankyrase expression increases Axin1 and Axin2 protein levels and attenuates Wnt-induced transcriptional responses in several breast cancer lines." (PMID 23144924, 2012). "Likewise, positive AXIN1 expression levels were lower in breast carcinomas, and AXIN1 expression inversely correlated with tumor size, histological grade, clinical tumor, node, metastasis stage, and lymph node metastasis." (PMID 38291457, 2024). "In breast cancer, the transcriptional repression of AXIN1 by ERα is antagonized by RUNX1." (PMID 38291457, 2024). "A previous study has suggested that TGIF1 could sequestrate Axin1/2 in the nucleus to prevent the assembly of the destruction complex, thereby promoting Wnt signaling in breast cancer cells." (PMID 29050273, 2017).
breast carcinoma (continued). "A recent report documented that Axin1 expression is decreased in breast cancer." (PMID 26908451, 2016). "Finally, RUNX1 loss-mediated deregulation of β-catenin and mitosis is ameliorated by AXIN1 stabilization in vitro, highlighting AXIN1 as a potential target for the management of ER+ breast cancer." (PMID 26916619, 2016). "As such, stabilization of Axin1 may lead to decreased tumor burden in breast cancer." (PMID 26908451, 2016). "In this study, by depleting RUNX1 in vitro and in vivo, we expose a link between oestrogen and β-catenin in ER+ breast cancer, that is, RUNX1-gated oestrogen-mediated AXIN1 transcriptional repression." (PMID 26916619, 2016). "This study demonstrates combinatorial regulation of AXIN1 by RUNX1 and oestrogen signalling in ER+ breast cancer cells." (PMID 26916619, 2016). "We selected AXIN-1, FAS, and FGFR2 for further analysis because of their known role in breast cancer and apoptosis." (PMID 23758675, 2013). "Analysis of expression in the TCGA confirmed lower expression of PRKAR1A in the basal‐like subtype and showed that AXIN1 levels did not change appreciably across subtypes of breast cancer." (PMID 35000262, 2022). "The negative correlation between RBM5-AS1 and AXIN1 expression was identified in breast cancer tissues from Starbase database or collected by us and the IHC staining in mice tumor section." (PMID 35110544, 2022). "Previous investigations had reported that TSC2, ARID1A, AXIN1, CASP8, CDH1, and ASXL1 could play roles in tumor suppression in diverse cancer types, including breast cancer." (PMID 29414922, 2018). "As shown here, CDK3 exhibited a potent inhibitory effect on Wnt signaling in breast cancer cells through regulating the phosphorylation level of LRP6, the expression of Axin1 and Dvl2, leading to the inhibition of β-catenin, and this process is possibly due to decreased expression of Wnt3a." (PMID 29156693, 2017). "AXIN1 mRNA significantly correlated with the RUNX1 inhibitory index in ER+ but not in the ER− breast cancer types." (PMID 26916619, 2016). "To address the combinatorial regulation of AXIN1 by RUNX1 and oestrogens in clinical settings, we first calculated an ‘inhibitory index' for RUNX1 in each tumour in the breast cancer cohort of TCGA20 based on the expression levels of genes that RUNX1 inhibited in MCF7 cells (see ‘Methods' section)." (PMID 26916619, 2016). "In ER+ breast cancer, however, RUNX1 predominantly functions as a tumour suppressor, and the present work attributes this function at least in part to antagonism of oestrogen-mediated AXIN1 suppression." (PMID 26916619, 2016).
gastric cancer (23 papers, 2012 to 2025). A primary or metastatic malignant neoplasm involving the stomach. "Peng's team found that circAXIN1 expression was increased in gastric cancer tissues and promoted the proliferation and migration of gastric cancer cells by encoding the novel protein AXIN1‐295aa." (PMID 37070530, 2023). "In addition, circAXIN1 encodes a 295-amino-acid protein, AXIN1-295aa, which appears to activate the Wnt signaling pathway, thereby promoting tumorigenesis and the progression of gastric cancer." (PMID 40649179, 2025). "Additionally, circAXIN1, highly expressed in gastric cancer tissues and cell lines, encodes a 295aa protein, AXIN1-295aa." (PMID 39333489, 2024). "Furthermore, the study by Peng and coworkers demonstrated that the 295-residue AXIN1 protein encoded by circAXIN1 promotes the progression of gastric cancer by activating the Wnt signaling pathway." (PMID 37633920, 2023). "Similarly, based on circRNA sequencing data, circAXIN1 was found to be highly expressed in gastric cancer (GC), and it encoded the protein AXIN1-295aa." (PMID 36358616, 2022). "Indeed, different components of the Wnt pathway have been shown to be mutated or dysregulated in gastric cancer, including Wnt1, SFRPs, Axin1 and Axin2, APC, GSK3-β, and β-catenin." (PMID 28230774, 2017). "This Axin1 depletion activates the Wnt/β-catenin signaling axis, accelerating gastric cancer (GC) initiation and progression." (PMID 40936722, 2025). "In gastric cancer, somatic mutations in CTNNB1 (encoding β-catenin), as well as inactivation of negative regulators such as APC and AXIN1, lead to constitutive β-catenin stabilization, nuclear accumulation, and persistent activation of Wnt target genes." (PMID 40649179, 2025). "TRIM31 promotes gastric cancer cell proliferation and invasion through activating the Wnt/β-catenin pathway by regulating Axin1 protein stability." (PMID 40919166, 2025). "Collectively, these findings underscore that TRIM11 contributes to gastric cancer progression by strengthening β-catenin activity through targeted degradation of Axin1, thereby driving tumor growth and invasiveness." (PMID 39768197, 2024). "Dysregulated Wnt signaling affects almost 50% of gastric cancers, with the most commonly mutated genes being RNF43, AXIN1/2, CTNNB1, and APC." (PMID 39191487, 2024). "Mechanistically, another study indicated that TRIM11 can destabilize Axin1 and promote its degradation via ubiquitination, resulting in the β-catenin pathway activation in gastric cancer cells and lymphoma cells." (PMID 39768197, 2024). "In addition, circ-AXIN1-encoded AXIN1-295aa competitively interacted with APC, resulting in activation of Wnt signaling pathway in gastric cancer cells." (PMID 37783059, 2023). "Indeed, genetic mutations in components of this pathway such as APC, AXIN1/2 and CTNNB1 are well-established molecular events in colorectal, as well as gastric carcinomas and HCC." (PMID 22768190, 2012). "Moreover, it has been reported that TRIM11 is involved in the activation of the β-catenin pathway via the ubiquitination and degradation of Axin1 in lymphomas and that it promotes cell growth and epithelial-mesenchymal transition in gastric cancer by activating β-catenin signaling." (PMID 35237324, 2022). "Given the central role of dysregulated Wnt signaling in oncogenesis, the ability of AXIN1-295aa to disrupt β-catenin turnover and sustain pathway activation suggests that it may significantly contribute to tumorigenesis and disease progression in gastric cancer." (PMID 40649179, 2025). "With increased expression in human gastric cancer tissues and cell lines (BGC-823 and HGC-27), TRIM31 was validated to ubiquitinate Axin1 for degradation to activate the Wnt/β-catenin pathway." (PMID 39768197, 2024). "This interaction leads to a decrease in the binding between AXIN1 and APC, consequently elevating β-catenin activity, which further contributes to the progression of gastric cancer." (PMID 39333489, 2024).
gastric cancer (continued). "Furthermore, circAXIN1 encodes AXIN1-295aa, which can competitively bind to APC to prevent the formation of the AXIN1-APC-GSK3B complex and activate the β-catenin signaling pathway to promote gastric cancer progression." (PMID 39103892, 2024). "In addition, NKX6.3 induced β-catenin binding to the β-catenin destruction complex, including GSK3β, Axin1, APC, and β-Trcp, in NKX6.3 stable gastric cancer cells." (PMID 27333045, 2016).